IL2 (interleukin 2)
Diseases named in the same sentence as IL2 in open-access papers (continued):
Sharing a sentence is not in itself a finding about the gene and the disease.
tumor (continued). "Joint decrease in IL-2 and IL-4 could be inducing a decrease in certain Tregs function after NAC, which would explain the stromal and tumor decrease in FoxP3 reported here, as well as the significant association between post-NAC expression of IL-10 and IL-17 and failure to obtain pCR." (PMID 37104271, 2023). "The interaction between PD-L1 expressed in tumor cells and PD-1 expressed in T cells inhibits the activity of effector T cells and increases the secretion of proinflammatory cytokines, such as tumor necrosis factor (TNF)-alpha, interleukin (IL)-2, and interferon-gamma (IFN-γ)." (PMID 36674491, 2023). "In addition, proinflammatory cytokine (IFN-γ, IL-2, IL-18, TNF-α) and cytolytic protein (granzyme A, granulysin) levels were analyzed and showed an initial increase during the early stage of the tumor and then decreased, corresponding to the clinical features of HCC patients." (PMID 37215109, 2023). "Finally, we did not analyze such serum cytokines as IFN-gamma, IL-2, IL-15, and IL-12, which can increase tumor cell class I MHC expression and sensitivity to lysis by CTLs or tumoricidal capacity of NK cells." (PMID 37894429, 2023). "In addition, the supernatant levels of T cell‐derived cytokines interleukin‐2 (IL‐2) and interferon‐γ (IFN‐γ) were remarkably upregulated in B3Z T cells cocultured with RA‐pretreated tumor cells, concurrently accompanied with increased expression level of T cell activation marker CD69." (PMID 36876644, 2023). "Liposomal nanoparticles with IL-2 and TGF β can mediate macrophage and NK cell homing and infiltration in the tumor site, and nanocomposite containing IFNγ or IL-2 can facilitate the conversion of immunosuppressive TME to more immunoresponsive environment enhancing NK tumor recognition and killing." (PMID 36834917, 2023). "Cluster 8 and cluster 12, which have high-risk scores and mostly appeared in the middle stages of LUAD (12w and 18w), showed more cellular response (such as IL2, IL6), and the abilities were lost with tumor progression, which could be related to the tumor progression." (PMID 36387251, 2022). "Th1 mediates anti-tumor immunity mainly by expressing CD40L and secreting cytokines such as INFγ and IL-2 to recruit and activate macrophages and cytotoxic T cells, which may be involved in the upregulation of TIL, macrophages and type II IFN response in geneCluster C." (PMID 36032135, 2022). "Alternatively, the competitive advantage of CD8 T cells with self-production of IL-2, even within environments of enriched IL-2 available, suggests that targeting production to CD8 T cells themselves may drive the desired response, for instance in a tumor setting." (PMID 35699942, 2022). "Compared to unmodified conventional IL-2, bempegaldesleukin leads to more CD8+ T cell and NK cell activation/expansion and less Treg expansion and is, thus, hypothesized to have increased anti-tumor activity and reduced toxicities." (PMID 36230766, 2022). "In one study that highlighted this immune-regulation potential, Glycyrrhiza polysaccharide was fed to CT-26 tumor-bearing mice and significantly inhibited tumor growth, increased the immune organ index, activated CD4+ and CD8+ immune cells, and increased levels of IL-2, IL-6, and IL-7 cytokines." (PMID 36090181, 2022). "Previously, it was reported that the prolonged infusion of low-dose IL-2 after HSCT could suppress tumor relapse without developing GVHD." (PMID 35983059, 2022). "For example, the Se-enriched Grifola frondosa polysaccharide could enhance the thymus and spleen indices of the tumor-bearing mice, increase both serum tumor necrosis factor-α (TNF-α) and interleukin-2 (IL-2) levels, and also promote nitric oxide (NO) production and macrophage phagocytosis." (PMID 36235602, 2022).
tumor (continued). "Notably, this TNFα- and IL-2-armed OV demonstrated synergy with mesothelin specific CAR T cells in a preclinical mouse model of pancreatic cancer, supported CAR T cell activity, with enhanced tumour regression and survival and prevention of metastases." (PMID 35205725, 2022). "The secretion of IL-2 and IFNγ were measured and found to be very low when the tribodies were used in the absence of tumor cells, thus suggesting that the tribodies do not activate naïve T cells not expressing high levels of ICs and do not elicit off target cytokine release." (PMID 36071464, 2022). "Meanwhile, Cal/ICG@MPs significantly promoted DC maturation and tumor infiltration of CD8+ T cells, activated CD8+CD69+ T, CD8+IFN-γ+ T and CD8+ IL-2+ T cells, while decreased the ratios of Tregs and PMN-MDSCs in the contralateral tumors upon 808 nm laser irradiation." (PMID 35589680, 2022). "In addition, in experimental studies, the combination of 1D11 mAb with IL-2 has allowed the administration of lower non-toxic doses of IL-2, while still maintaining strong anti-tumor responses mediated by both NK and CD8 T cells on tumor mouse models." (PMID 36231109, 2022). "Here, we explore small-format IL-2 immunocytokines with affinity to the tumor extracellular matrix, a major component of the tumor microenvironment, rather than cell-surface antigens of tumor cells." (PMID 36712341, 2022). "Transfection of cytokines such as interleukin-2 generated in vivo immunity to the mesothelioma tumor that was relatively weak and/or subject to down-regulation so that consistent rejection of unmodified parental tumor cells was not achieved." (PMID 35431929, 2022). "We found that the levels of cytokines, including IL-2, IFN-γ and TNF-α, were very low in tumours treated with AXL-CAR T cell monotherapy, suggesting that mono-CAR T cells were hypofunctional and/or that the absolute number of AXL-CAR T cells responding to the tumour cells was low." (PMID 36261437, 2022). "IL‐2 is an important broad‐spectrum enhancer in the body that can enhance the activity of natural killer cells, and induce T lymphocytes to produce IFN, activating immune effector cells and producing synergistic effectors, that can effectively remove tumor and virus/bacteria‐infected cells." (PMID 36348789, 2022). "In this context we did not test mixtures of individual vectors (LV-shFDPS + LV-shFDPS-IL2 in varying ratios) to see whether a lower proportion of IL2 producing tumor cells would support Vδ2 T cells effects without the associated toxicity." (PMID 36275712, 2022). "However, treatment with high-dose IL-2 leads to off-target effects, particularly Tregs, which are considered as a negative prognostic factor in some tumor types by dampening antitumor responses." (PMID 35651800, 2022). "Finally, we find that simply having an immune cell that can individually produce high levels of IL-2 in the tumor is not sufficient to overcome suppression." (PMID 36520915, 2022). "We have previously shown that tumor cells expressing mHsp70 can be recognized and killed using NK cells that have been activated by ex vivo incubation with a 14-mer Hsp70-derived peptide (TKDNNLLGRFELSG, ‘TKD’) and low-dose IL-2 (100 U/ml for 3-5 days) in a wide range of different cancer settings." (PMID 35720311, 2022). "The polysaccharides could activate macrophages, T-lymphocytes, B-lymphocytes, natural killer cells, and cytokines that are closely related to the killing of the tumor, such as tumor necrosis factor (TNF-α), interferon (IFN-γ), and interleukins (IL-2, IL-4, IL-6, and IL-12)." (PMID 35295918, 2022). "IL-2 promotes the expansion of regulatory T cells, therefore, the FLOT and CROSS chemotherapy-induced decrease in IL-2 production by T cells may in turn decrease regulatory T cell expansion and support development of anti-tumour immunity." (PMID 35366537, 2022).
tumor (continued). "There was a significant increase (p<0.001) in the levels of IFN-γ, IL-2, granzyme B, and CD107a in CD8+ T cells, indicating that inhibition of PD-L1 secretion from tumor cells contributed to CD8+ T cell activation and could help restore CD8+ T cell proliferation." (PMID 35228265, 2022). "As the immune system is activated, a series of representative cytokines interleukin-2 (IL-2), IL-10, IL-12, IL-1β, interferon γ (IFN-γ), tumor necrosis factor α (TNF-α) of T cells that regulate the immune response in the serum significantly increased, improved the anti-tumor immunity." (PMID 35651605, 2022). "Several potential mechanisms may have led to this advantage, one was that MWA could have increased the probability of CD8+ tumor infiltrating lymphocytes (TIL) and Natural killer (NK) cells, and the other was that MWA could have increased the peripheral IL-2 and IFN-γ." (PMID 36091128, 2022). "Thus, we hypothesized that providing IL-2 in a tumor-targeted, but TCR/CAR-independent manner, could help bypass tumor immune suppression." (PMID 36520915, 2022). "Mechanically, an inflammatory TME was the basis of immune-inflamed phenotype, also known as a hot tumor, containing pro-inflammatory cytokines which provided a more favorable condition for T cell activation and expansion, including type I and type II interferons, TNF-α, IL-2, and IL-12." (PMID 36276973, 2022). "Restimulation of expanded TILs with autologous tumor cells revealed that GEN1046-expanded CD8+ TILs contained greater proportions of cells that upregulated 4-1BB and IFNγ/CD107a upon restimulation compared with atezolizumab and IL2 alone, which was dependent on MHC I." (PMID 35176764, 2022). "In addition, in a recent study, macrophage depletion using the F4/80 antibody in elderly mice improved the IL-2/anti-CD40 treatment response and achieved up to 78% tumor regression compared to 38% tumor regression in the intact macrophages control and reduced age-related treatment-induced cachexia." (PMID 36679900, 2022). "However, CAR T cells from patients who responded to therapy exhibited superior expansion and produced higher levels of IL-2 after a 5-day exposure to CD19 expressing tumor cells compared to CAR T cells obtained from patients not responding to CAR T cells." (PMID 35406703, 2022). "However, despite expecting the highest anti-tumor effect with the TBI/IL-2 combination, no additive effect was observed in the treated animals." (PMID 36497152, 2022). "Administration of IL-2 into wild-type mice enhanced FBXO38 levels in tumors-infiltrating T cells and down-regulated PD-1 from their surface, resulting in more efficient anti-tumor responses, even when IL-2 simultaneously increased, by activating T cells, PD-1 mRNA transcription." (PMID 34639141, 2021). "Combination with F8-IL2, a tumor-targeted version of human IL2, did result in substantially improved therapeutic effect, which was, however, not superior to F8-IL2 monotherapy, suggesting that IL2 preferentially acted on the preexisting immune infiltrate, rather than on injected T cells." (PMID 33796916, 2021). "It is not easy to specifically determine IL-2 level generated by immune cells in tumor tissues." (PMID 34830445, 2021). "IL2Rα failed to block this mutant IL-2, likely activating CTLs before reaching tumor tissues." (PMID 33986267, 2021). "Given the rapid development of tumor immunology, a large number of previous studies had found that traditional immunotherapy, such as IFN-α and IL-2, could extend the OS to a certain extent, but their response duration was limited, and only a few patients could fully respond." (PMID 35155566, 2021).
tumor (continued). "Thus, the addition of both ASA and low-dose IL-2 to the OCDC-Bev-Cy combinatorial regimen induced a Th1-polarizing sera chemokine profile, particularly CXCL9 that was conducive for the recruitment of CD3+ and CD8+ TILs for tumor control." (PMID 33723260, 2021). "Tumor growth factors (e.g., EGF, PDGF-α, PDGF-β, HGF, and GDF-15), chemotactic factors (e.g., CXCL9 and CCL-25), matrix metalloproteinases (MMP1, MMP3, and MMP9), and inflammatory cytokines (IL-1β, IL-2, and IL-7) were discovered in liver tumors to chemoattract MSCs." (PMID 34603454, 2021). "The main effectors of Th1 cells are interleukin (IL)-2 and interferon (IFN)-γ, which can indirectly or directly promote and maintain the proliferation and activation of T cells, induce and enhance the anti-tumor activity of NK cells, and inhibit the division and proliferation of tumor cells." (PMID 35082830, 2021). "Cytokines such as IL-6, IL-8, and IL-2 were found to be up-regulated as well in culture supernatants of MCF-7 following treatment with zerumbone and paclitaxel, this will further contribute to promoting inflammation that will eventually activate the host immune response against tumor." (PMID 35317109, 2021). "In addition, in vitro experiments followed by quantitative real‐time polymerase chain reaction (qRT–PCR) assays showed that SLAMF8 mRNA was mainly expressed on human macrophages and T cells activated by IL‐2 but not on tumor cells." (PMID 34729183, 2021). "In addition, lack of tumor-targeted release of PEGylated IL-2 results in toxicity before reaching therapeutic doses, which limits repeatable results and significant objective responses in clinical trials." (PMID 33986267, 2021). "This 45-nucleotide long aptamer could recognize both murine and human PDL1 and modulate the tumor microenvironment by elevated CD4+ and CD8+ T cell infiltration and IL2, IFNγ, TNFα and other chemokine expression at the tumor site, which might form a loop against tumor proliferation." (PMID 34575825, 2021). "In addition, Ciji-Hua’ai-Baosheng improved the immune function of H-22 tumor-bearing mice after treatment with chemotherapy and alleviated CTX-induced colitis, manifested as elevated lymphocytes in spleen, augmented IL-2, IFN-γ and TNF-α, and the reduced IL-6 in serum and tumor tissues." (PMID 34722304, 2021). "These tumor cells escape from the immune system by the use of BTLA–HVEM pathway since impeding the signaling of BTLA–HVEM in the cell culture of naive mice splenocytes with B16F1 cells ameliorates specific cytotoxicity to B16F1 cells and the synthesis of IL-2 and IFN-γ." (PMID 32902664, 2021). "This process included the isolation of tumor-infiltrating T cells from a tumor specimen and the stimulation of T cells by neoantigen-loaded dendritic cells, followed by single-cell sequencing for TCR and T-cell activation markers, interferon-γ and interleukin-2." (PMID 34321276, 2021). "Emphasizing the importance of the tumor microenvironment (TME) and reflecting concerns that systemic IL-2 can expand Treg populations, the group went on to demonstrate improved persistence and response rates of >50% with prior depletion of Treg cells using a recombinant IL-2-diptheria toxin protein." (PMID 33805422, 2021). "However, the role of IL-2 in activation induced cell death (AICD), and in promoting the accumulation of Tregs, especially at low doses, partially counteracts its anti-tumor effectiveness." (PMID 33671252, 2021). "We acknowledge that it is not fully clear how IL-2 and imiquimod may act in conjunction to mediate these anti-tumor immune responses; this merits further mechanistic study." (PMID 34122442, 2021). "In multiple in vitro and murine tumor models, PD1/PDL1 blockade in combination with an agonist CD27 monoclonal antibody was shown to enhance CD8+ cytotoxic T-cell expansion and function in an IL-2 dependent manner with gene expression changes promoting T-cell proliferation." (PMID 34630390, 2021).
tumor (continued). "Therefore, we created another mouse model with host NK cells present but inhibited in their effector function by HLA-Cw3 ligand present on tumor cells and then injected IL-2 NK cells lacking inhibitory receptors for HLA-Cw3." (PMID 34071607, 2021). "Hence, it would be important to address whether IL2Rα-tumor cells additionally express CD122 and CD132, and are responsive to IL2 signals." (PMID 33498681, 2021). "Interestingly, the intratumoral injection of apoptotic tumor cells with IL-2 led to an 80% rate of cure in mice models, confirming that the APC in the TME retain the intrinsic capacity to uptake, present, and generate a tumor-specific cytotoxic T cell response." (PMID 34572013, 2021). "Indeed, PD-L1_1 plus ID-1 treatment showed potent effects on tumor cells lysis, reaching 100% of lysis in co-cultures of MDA-MB-231 cells and inducing a higher secretion of IL-2 and IFN-γ with respect to atezolizumab and ipilimumab, but exerted opposite effects on cardiomyocytes." (PMID 35008285, 2021). "The results showed that IL-2, IL-12, IL-17, TNF-α, and INF-Υ, which were immunity promoting cytokines, were significantly upregulated in drug serum, while IL-10, TGF-β, VEGF, and MMP-9, which were immunity abating or tumor promoting proteins, were significantly downregulated in drug serum." (PMID 33505491, 2021). "IL-2 treatment alone in mice did not have a significant effect on tumor growth (data not shown)." (PMID 34172810, 2021). "Furthermore, during melanoma progression, the expression of CD40L on tumor-infiltrating CD4+ T cells, as well as the expression of interferon (IFN-)γ, tumor necrosis factor (TNF-)α, and IL-2 by these cells, was inhibited, accompanied by increased numbers of Treg and MDSC in the tumor." (PMID 34576054, 2021). "Interestingly, the same combination with cisplatin did not change the tumor growth but the triple combination (IL2-NHS, RT, cisplatin) resulted in the largest antitumor effect, controlling 83% of these aggressive tumors." (PMID 33806808, 2021). "Suppression of TNBC lung metastasis by resveratrol may be through elevating local antitumor immunity, as revealed by an increase in the levels of type 1 cytokines, including IFN-γ and IL-2 in the lung and infiltration of CD4+ and CD8+ T cells to the lung of resveratrol-treated tumor bearing mice." (PMID 34948368, 2021). "Moreover, none of the IL-10, IFN-γ, or IL-2 level was correlated with tumor size (r = 0.024, p = 0.925; r = −0.115, p = 0.568; and r = −0.232, p = 0.276, respectively)." (PMID 34257554, 2021). "However, anti-4-1BB antibody, IL-2, and IL-9 failed to reduce tumor burden in the Myc-CaP CRPC tumor model." (PMID 34771735, 2021). "However, a pilot study of progressive platinum-resistant OC demonstrated minimal anti-tumour effects with ACT following lymphodepletion and IL-2 therapy, with four out of six patients showing stable disease for only three months and two out of six patients for five months." (PMID 34944851, 2021). "IL-2 is an important factor for maintenance of CD4+ regulatory T cells, but also plays a critical role in the proliferation and differentiation of CD4+ T cells, promotion of CD8+ T cell and NK cell cytotoxic activity, and modulation of T cell differentiation programs in response to tumor antigens." (PMID 33807849, 2021). "In vivo, orthoIL-2 could expand tumor-specific T cells expressing orthoIL-2Rβ to control tumor growth without the dose-limiting toxicity seen with high doses of IL-2." (PMID 34177932, 2021). "Moreover, the IL-2 gene and protein expression measured in this study were the total IL-2 expressed by both tumor and non-tumor cells in the tumor immune microenvironment." (PMID 34830445, 2021). "IL-2 could not be detected in tumor cells of 33 ALCL patients nor in ALCL cell lines, suggesting other sources of IL-2 in ALCL." (PMID 34552066, 2021).